EDIL3 (EGF like and discoidin domains 3)
Description:
Promotes adhesion of endothelial cells through interaction with the alpha-v/beta-3 integrin receptor. Inhibits formation of vascular-like structures. May be involved in regulation of vascular morphogenesis of remodeling in embryonic development.
Synonyms: DEL1
Tractability: Antibody: its Gene Ontology location is reachable by antibodies, with high confidence; UniProt places it where antibodies can reach, with medium confidence; UniProt predicts a signal peptide or a membrane-spanning region. PROTAC: ubiquitination databases record sites on it; its protein half-life has been measured.
Gene: Protein-coding gene on chromosome 5 (83,940,554 to 84,384,885, reverse strand). Ensembl gene ENSG00000164176.
Subcellular location: Secreted
Subcellular location (Human Protein Atlas): Plasma membrane; Predicted to be secreted
Pathways (Reactome):
Developmental Biology: Regulation of MITF-M-dependent genes involved in extracellular matrix, focal adhesion and epithelial-to-mesenchymal transition
Gene Ontology:
Molecular function: extracellular matrix structural constituent; integrin binding; calcium ion binding
Biological process: positive regulation of cell-substrate adhesion
Cellular component: extracellular exosome; extracellular matrix; extracellular vesicle; extracellular region; non-collagenous component of interstitial matrix
Genetic constraint (gnomAD): Loss-of-function variants: 37 observed, 69.07 expected, observed/expected ratio (o/e) 0.54, 90% interval 0.41 to 0.7. The upper end of that interval is the gene's LOEUF score, 0.7, which puts it in group 2 of 6, group 1 being the genes least tolerant of losing a copy. Missense variants: 527 observed, 610.35 expected, observed/expected ratio (o/e) 0.86, 90% interval 0.8 to 0.93. Synonymous variants: 195 observed, 203.07 expected, observed/expected ratio (o/e) 0.96, 90% interval 0.85 to 1.08.
Homologues: Orthologues: chimpanzee EDIL3 (99% identical), dog EDIL3 (96% identical), rat Edil3 (96% identical), mouse Edil3 (96% identical), rabbit EDIL3 (96% identical), pig EDIL3 (95% identical), guinea pig EDIL3 (93% identical), macaque EDIL3 (90% identical), tropical clawed frog edil3 (85% identical), zebrafish edil3a (79% identical), zebrafish edil3b (70% identical). Paralogues in human: MFGE8 (41% identical), CNTNAP5 (24% identical), CNTNAP3 (21% identical), CNTNAP4 (21% identical), CNTNAP3B (21% identical), CNTNAP2 (21% identical), F5 (20% identical), F8 (20% identical), NRXN2 (20% identical), CUBN (19% identical), HEPHL1 (18% identical), CNTNAP1 (18% identical), and 23 more.
Diseases named in the same sentence as EDIL3 in open-access papers:
EDIL3 is named in the same sentence as 111 diseases in open-access papers, as found by Europe PMC text mining. Sharing a sentence is not in itself a finding about the gene and the disease. The quoted sentences say what the papers report.
breast carcinoma (35 papers, 2009 to 2025). "Conversely, paclitaxel resistance is strongly related to the induction of EMT and the high expression levels of EMT-related genes, such as the EDIL3 gene in breast cancer cells." (PMID 39003454, 2024). "Expression analysis revealed that EDIL3 expression was elevated in many types of tumors, including hepatocellular carcinoma, pancreatic adenocarcinoma, colorectal cancer, and breast cancer, while the expression of EDIL3 decreased in non-small cell lung cancer." (PMID 37576496, 2023). "Together these results further confirm that extracellular EDIL3 regulates paclitaxel response in breast cancer cells." (PMID 33014430, 2020). "We performed a differential gene expression analysis comparing paclitaxel-resistant vs. paclitaxel-sensitive breast cancer cells that showed the upregulation of EDIL3 (EGF Like Repeats and Discoidin I Like Domains Protein 3)." (PMID 33014430, 2020). "First, we studied the protein expression levels of EDIL3 in five breast cancer cell lines, which show differences in paclitaxel sensitivity." (PMID 33014430, 2020). "Recently, EDIL3 expression has been observed in several tumor types, including breast cancer, in which this protein has been identified as a biomarker for early disease detection." (PMID 33014430, 2020). "In breast cancer, out of 53 grades I and II breast tumors, 35 (66.0%) expressed low levels of EDIL3, while out of 36 grade III breast tumors, 21 (58.3%) expressed high levels of EDIL3." (PMID 33014430, 2020). "In summary, paclitaxel-resistant breast cancer cells overexpressed EDIL3 and, surprisingly, these cell lines had a mesenchymal phenotype." (PMID 33014430, 2020). "Developmental endothelial locus-1 (Del-1), also referred to as epidermal growth factor-like repeats, and discoidin domains-3 (Edil-3), is widely expressed in breast cancer." (PMID 31817673, 2019). "The levels of exosomal fibronectin and developmental endothelial locus-1 (EDIL3) were significantly higher in breast cancer patients than controls and dramatically reduced after tumor resection, suggesting that they may serve as important diagnostic and prognostic markers for breast cancer patients." (PMID 29282096, 2017). "The levels of exosomal EDIL3 and fibronectin from breast cancer patients who underwent surgery were dramatically reduced, suggesting that EDIL3 and fibronectin in circulating EVs can also serve as treatment response markers." (PMID 28085080, 2017). "The discovery of high EDIL-3 concentration in metastatic breast cancer suggests that this protein could potentially serve as a stage-specific biomarker, detectable through circulating EVs." (PMID 40006624, 2025). "In addition, exosomes containing EDIL-3 play a significant role in the metastasis process of breast cancer, affecting nearby organs such as the lungs." (PMID 40006624, 2025). "Interestingly, EDIL3 expression was found to be present in different tumor types, such as breast cancer." (PMID 39411143, 2024). "In addition to breast cancer, EDIL3 expression increases in hepatocellular carcinoma and predicts a poor prognosis." (PMID 34217213, 2021). "Although different protein expression levels of EDIL3 were observed in these breast cancer cell lines, the statistical analysis showed that when compared with MDA-MB-468 cells, only MDA-MB-468R and MDA-MB-231 cells had a significant increase in EDIL3 protein expression." (PMID 33014430, 2020). "Also, EDIL3 has been identified in the extracellular vesicles of breast cancer cells that may be used for early breast cancer detection in the plasma of patients." (PMID 33014430, 2020). "For example, EDIL3 is involved in the progression of breast and bladder cancers), while TGM2 mediates chemoresistance of both lymphoma and breast cancer." (PMID 31416147, 2019).
breast carcinoma (continued). "Since EDIL3 interacts with integrin αVβ3 and other ligands of this integrin are secreted to the ECM and present an autocrine regulation mechanism, we investigated whether EDIL3 was secreted to the medium by breast cancer cells expressing different levels of EDIL3." (PMID 33014430, 2020).
periodontitis (22 papers, 2013 to 2024). An acute or chronic inflammatory process that affects the tissues that surround and support the teeth. "EDIL3-/- mice have a specific phenotype characterized by increased development of spontaneous periodontitis." (PMID 36518760, 2022).
bladder cancer (16 papers, 2014 to 2025). "Exosomal EDIL-3 has been shown to be overexpressed in urine samples of bladder cancer patients and its levels are associated with pathologic grade." (PMID 37805491, 2023). "Exosomal EDIL-3 was one of the proteins that activated epidermal growth factor receptor signaling, inducing bladder cancer cell migration." (PMID 37805491, 2023). "Following EDIL-3 knock-down in bladder cancer cells, the collected EVs had lower EDIL-3 levels, and were unable to promote angiogenesis and migration." (PMID 32485907, 2020). "In bladder cancer, exosomes isolated from the urine of high-grade bladder cancer patients had higher levels of EDIL-3, a molecule that promotes angiogenesis, compared to exosomes from healthy individuals." (PMID 25883534, 2015). "Indeed, extracellular vesicles isolated from high grade bladder cancer cells, and from the urine of patients with high grade bladder cancer, contained EDIL-3 and increased angiogenesis and migration of bladder cancer and endothelial cells." (PMID 32485907, 2020). "Indeed, when EVs originate from high grade bladder cancer cells isolated from the urine of patients submitted to radical cystectomy, EVs contain substantially higher levels of EDIL-3, a pro-angiogenesis and migration protein, than healthy controls." (PMID 32485907, 2020). "Beckham and coworkers further elucidated that exosomal EDIL-3, a protein with a known role in angiogenesis and abundantly present in cancer-derived exosomes of both bladder cancer cell lines and bladder cancer patient samples, was necessary to induce tube formation." (PMID 28796150, 2017). "We selected generic exosome markers CD9, CD63, and TSG101, as well as the EDIL-3 and MUC4 for Western blotting analysis of urinary exosome proteins prepared by UC and NanoPoms methods, with the human bladder carcinoma cell line HTB9 as the control." (PMID 35787656, 2022). "On the other hand, EDIL3 (EGFR-activating, proangiogenic integrin ligand) was previously identified in exosomes from invasive bladder cancer cell lines and from urine of patients with high-grade UBC." (PMID 34202855, 2021). "Protein biomarkers including EDIL-3 (EGF-like repeats and discoidin I-like domains 3) are highly expressed in exosomes derived from high-grade bladder cancer cells and promote tumor migration by activating the EGFR signaling pathway, positioning EDIL-3 as a potential therapeutic target." (PMID 41459253, 2025). "In addition, exosomes from patients with bladder cancer express elevated levels of EDIL-3/Del1, TACSTD2, LASS2, and GALNT1 with no expression of ARHGEF39 and FOXO3." (PMID 28659795, 2017).
hepatocellular carcinoma (11 papers, 2014 to 2025). A malignant tumor that arises from hepatocytes. "It has been reported that EDIL3 is overexpressed in several tumor types, including bladder, pancreas, breast, and liver carcinomas, and associates with tumor progression and poor prognosis." (PMID 33014430, 2020). "EDIL3 is an inducer of the epithelial-mesenchymal transition, that promotes angiogenesis and invasion in hepatocellular carcinoma." (PMID 33245713, 2020). "Blocking the TGF-beta and ERK signaling pathway can effectively reduce EDIL3-mediated angiogenesis and invasion in a hepatocellular carcinoma mouse model." (PMID 28819306, 2017). "And recently it has also been reported that EDIL3 was regulated by miR-137 in hepatocellular carcinoma." (PMID 26735172, 2016). "Consistent with the findings in hepatocellular carcinoma, EDIL3 expression was up-regulated during malignant transformation in PDAC." (PMID 26735172, 2016). "In hepatocellular carcinoma, elevated autocrine EDIL3 protects cancer cells from anoikis through RGD-mediated integrin activation." (PMID 26735172, 2016). "And in line with our previous observations in hepatocellular carcinoma, EDIL3 promoted anoikis resistance and anchorage-independent growth of pancreatic cancer cells." (PMID 26735172, 2016). "In hepatocellular carcinoma, EDIL3 exhibits its roles through activation of FAK-Src-Akt signaling by interacting with αvβ3 integrin." (PMID 26735172, 2016). "The secreted glycoprotein EDIL3 has recently been identified as a novel inducer of EMT in hepatocellular carcinoma." (PMID 27144453, 2016). "Overexpression of EDIL3 in hepatocellular carcinoma could induce the phosphorylation of SRC, ERK, and SMAD2, leading to the activation of ERK and TGF-β signaling." (PMID 35096599, 2021). "However, it has been demonstrated that EDIL3 was expressed in multiple types of cancer including breast cancer, colon cancer, bladder cancer and hepatocellular carcinoma." (PMID 26735172, 2016).
melanoma (6 papers, 2009 to 2025). A malignant, usually aggressive tumor composed of atypical, neoplastic melanocytes. "Tabasum and colleagues recently deciphered the supportive role of EDIL3 leading to immune evasion through CD8+ T-cell exclusion in melanoma." (PMID 39411143, 2024).
multiple sclerosis (6 papers, 2015 to 2022). A progressive autoimmune disorder affecting the central nervous system resulting in demyelination. "EDIL3, the gene encoding Del-1, is believed to be a susceptibility gene for multiple sclerosis and Alzheimer’s disease." (PMID 34217213, 2021).
prostate carcinoma (6 papers, 2020 to 2025). A carcinoma that arises from epithelial cells of the prostate gland. "In this study, we demonstrated a significant association between EDIL3 protein expression and Gleason score in prostate cancer." (PMID 33014430, 2020). "Statistical analysis of these results showed a significant positive association between tumor grade and EDIL3 expression in breast and prostate cancers (P = 0.03 and P < 0.0001, respectively)." (PMID 33014430, 2020). "In prostate cancer, out of 28 low-grade (Gleason ≤ 7) prostate tumors, 20 (71.4%) expressed low levels of EDIL3, while out of 23 high-grade (Gleason 8–10) prostate tumors, 20 (87%) expressed high levels of EDIL3." (PMID 33014430, 2020). "Our results demonstrated that EDIL3 expression levels were increased in paclitaxel-resistant breast and prostate cancer cells, and in subsets of high-grade breast and prostate tumors." (PMID 33014430, 2020). "For that, EDIL3 expression was silenced using a specific pool of small interfering RNA (siRNA), and breast and prostate cancer cells were subsequently treated with 1 or 2.5 μM paclitaxel during 48 h, respectively." (PMID 33014430, 2020). "We also performed an immunohistochemical analysis of EDIL3 protein in tumor tissues from 89 breast and 51 prostate cancer patients." (PMID 33014430, 2020). "We observed high levels of EDIL3 protein in paclitaxel-resistant breast and prostate cancer cells that also showed a mesenchymal phenotype." (PMID 33014430, 2020). "Genes such as ASCL1, WDFY4, GLYATL2, and EDIL3, which are upregulated in CRPC, likely drive the progression from primary prostate cancer to CRPC." (PMID 40165961, 2025). "In conclusion, we show that high levels of EDIL3 play a prominent role in EMT, as well as in paclitaxel resistance in both breast and prostate cancer cells." (PMID 33014430, 2020). "Overall, these results suggest that EDIL3 regulates the paclitaxel response and EMT in both breast and prostate cancer cells via an autocrine or paracrine mechanism." (PMID 33014430, 2020). "EDIL3 has been reported to promote EMT in some breast and prostate cancers." (PMID 40430098, 2025). "Therefore, our data suggest that EDIL3 is a key regulator of EMT, and determines sensitivity to paclitaxel in breast and prostate cancer cells." (PMID 33014430, 2020).
colon cancer (5 papers, 2009 to 2023). "Downregulation of EDIL3 with small interfering RNA gene therapy has been shown to suppress the growth of colon tumors by inhibiting angiogenesis and cell proliferation in a mouse model." (PMID 28819306, 2017). "In colon cancer, down-regulation of EDIL3 inhibits tumor growth by anti-angiogenesis and anti-proliferation." (PMID 26735172, 2016). "The case is similar for EDIL3, which is positively associated with invasion capacity according to multiple linear regression analysis, but based on the HPA, higher tissue expression is associated with better 5-year survival in colon tumors." (PMID 37986165, 2023).
osteosarcoma (5 papers, 2015 to 2024). A usually aggressive malignant bone-forming mesenchymal neoplasm, predominantly affecting adolescents and young adults. "Combining the bioinformatics analysis results from this study, SQLE and EDIL3 are likely to be genes associated with risk, indicating a positive correlation between their high expression and the development of osteosarcoma cells." (PMID 39015570, 2024). "Bioinformatics analysis indicated a positive correlation between the high expression of SQLE and EDIL3 and osteosarcoma cell development." (PMID 39015570, 2024). "On the other hand, the expression levels of SQLE and EDIL3 genes were considerably higher in osteosarcoma samples compared to the adjacent normal tissues (P=0.033 and P=0.026, respectively)." (PMID 39015570, 2024). "Knockdown of SQLE and EDIL3 gene expression in osteosarcoma cells resulted in a significant decrease in proliferation and migration abilities, accompanied by a notable increase in apoptosis rate." (PMID 39015570, 2024). "Conversely, the protein expression levels of SQLE and EDIL3 were markedly elevated in osteosarcoma samples compared to the adjacent normal tissues." (PMID 39015570, 2024). "It has been demonstrated that EDIL3 can accelerate tumor growth by enhancing vascular formation and inhibiting tumor cell apoptosis in osteosarcoma and Lewis lung carcinoma." (PMID 26735172, 2016). "Further investigation into the regulatory mechanisms of risk genes, such as EDIL3 and SQLE, revealed that these genes are potential candidates for therapeutic targeting, as indicated by their significant role in the progression and prognosis of osteosarcoma." (PMID 39015570, 2024). "In osteosarcoma cells, both the mRNA and protein expression levels of SQLE and EDIL3 genes show significant elevation." (PMID 39015570, 2024). "Knockdown of three of these genes—CLTCL1, EDIL3, and SQLE—resulted in substantial changes in proliferation rate, migration capacity, and apoptosis rate of osteosarcoma cells." (PMID 39015570, 2024). "Specifically, EDIL3 and SQLE exhibited significant upregulation in osteosarcoma samples, suggesting their roles in promoting angiogenesis and cholesterol biosynthesis, respectively." (PMID 39015570, 2024). "Downregulation of EDIL3 and SQLE in the U2OS osteosarcoma cell line was essential for exploring potential treatment strategies and understanding osteosarcoma pathology." (PMID 39015570, 2024). "However, mRNA expression levels of EDIL3 and SQLE genes were markedly higher in osteosarcoma cell lines compared to MSCs." (PMID 39015570, 2024). "Compared to the control group, a significant decrease in the apoptosis rate of osteosarcoma cells was observed following CLTCL1 gene knockdown (P<0.001), while a substantial increase was noted after SQLE gene knockdown (P<0.001) and EDIL3 gene knockdown (P<0.01)." (PMID 39015570, 2024). "According to all experimental results, CLTCL1, MTM1, and MLH1 are likely tumor suppressor genes exerting inhibitory effects on osteosarcoma development, while SQLE and EDIL3 may function as targets promoting tumor proliferation, thus presenting new therapeutic potential." (PMID 39015570, 2024). "Additionally, when compared to MSC cell lines, human osteosarcoma cell lines showed significantly higher protein expression levels of SQLE and EDIL3, whereas CLTCL1 demonstrated significantly higher protein expression levels in MSC cell lines than in human osteosarcoma cell lines." (PMID 39015570, 2024).
Sepsis (5 papers, 2019 to 2025). Sepsis is defined as life-threatening organ dysfunction caused by a dysregulated host response to infection. "Edil3−/− (hereafter designated Del1−/−) neonate mice demonstrated enhanced neutrophil tissue infiltration but soon developed neutropenia in the blood as well as the bone marrow and exhibited worse survival in sepsis, when compared to DEL-1-sufficient neonate mice." (PMID 38263289, 2024).
breast tumor (4 papers, 2017 to 2023). "In addition, the EGF-Like Repeats and Discoidin I-Like Domains Protein 3 (EDIL3) was highly expressed in paclitaxel-resistant breast tumor, but low in sensitive breast tumor." (PMID 37299624, 2023). "EDIL-3 could activate EGF receptor (EGFR) signaling to promote bladder cell migration, and lysyl oxidase secreted by hypoxic breast tumor cells was considered to be a crucial mediator of pre-metastatic niche formation." (PMID 28706483, 2017).